EGFR (epidermal growth factor receptor)
Diseases named in the same sentence as EGFR in open-access papers (continued):
Sharing a sentence is not in itself a finding about the gene and the disease.
lung adenocarcinoma (continued). "EGFR mutations were more likely to occur in non‐smoking, stage III–IV, and female patients with lung adenocarcinoma, whereas ALK&ROS1 gene fusions were more likely to occur in young patients with lung adenocarcinoma." (PMID 35081265, 2022). "ANGPTL4 may be an effective new target for inhibiting EGFR-TKI resistance in lung adenocarcinoma cells." (PMID 36467503, 2022). "Nevertheless, deep learning models for the prediction of EGFR mutation in lung adenocarcinoma manifesting as pGGN have not been evaluated thus far." (PMID 36119545, 2022). "Besides, the LncRNA H19 SNP rs217727 are related to advanced tumor status for lung adenocarcinoma with EGFR wild type." (PMID 36011604, 2022). "Hence, routine testing for EGFR mutation status has become a standard-of-care recommendation for advanced NSCLC patients, especially those with lung adenocarcinoma histology." (PMID 36341427, 2022). "Therefore, in this study, the patients with advanced EGFR mutant lung adenocarcinoma, who received thoracic radiotherapy, were retrospectively recruited." (PMID 36153486, 2022). "The activation of NF-κB by the Wnt pathway was observed in a previous study of lung adenocarcinoma cells, where progesterone membrane component 1 conferred resistance to EGFR-targeted therapy and augmented the activity of the NF-κB pathway by upregulation of the Wnt pathway." (PMID 35744061, 2022). "Preclinical research suggested that EGFR inhibitors could increase the efficacy of immunotherapy in lung adenocarcinomas." (PMID 36254250, 2022). "The aim of the current study was to evaluate the combined effect of the single nucleotide polymorphism (SNP) in long non-coding RNA growth arrest-specific 5 (GAS5) and the phenotypes of epidermal growth factor receptor (EGFR) on the clinicopathological characteristics of lung adenocarcinoma." (PMID 36011604, 2022). "This is the first study highlighting the role of exosomes derived from EGFR-mutated lung adenocarcinoma (independent of stage, gender, age, or smoking history of patient) in the metastatic process." (PMID 35954442, 2022). "This indicated that SD had the effect of inhibiting the growth of lung adenocarcinoma cells, and the mechanism might be related to the inhibition of EGFR pathway." (PMID 35190747, 2022). "EGFR mutations occur most frequently in lung adenocarcinomas, women, never-smokers, and in Asian populations." (PMID 35444951, 2022). "Our patient’s response to alectinib, instead of to EGFR-TKIs, may lead to an expanded list of alectinib beneficiaries who have rare gene co-alterations in lung adenocarcinoma." (PMID 36107507, 2022). "Besides, miR-145 has been reported to suppress the proliferation of human lung adenocarcinoma cells by regulating EGFR." (PMID 35167433, 2022). "Thus, clinical features (young age, female, and non-smoker) traditionally considered to be significant factors for predicting EGFR in lung adenocarcinoma retain important roles in pGGN adenocarcinoma." (PMID 36119545, 2022). "In conclusion, this study suggests that EGFR mutations were more likely to occur in non‐smoking, stage III–IV, and female patients with lung adenocarcinoma, whereas ALK&ROS1 gene rearrangements were more likely to occur in young patients with lung adenocarcinoma." (PMID 35081265, 2022). "Moreover, the use of EGFR inhibitors in the setting of COVID-19 can be controversial, due to the previous reports of interstitial lung disease in patients with lung adenocarcinoma treated with EGFR tyrosine kinase inhibitors." (PMID 35937253, 2022). "The results have a great clinical significance, indicating that the increased local control of thoracic lesions in the advanced EGFR mutant lung adenocarcinoma can improve OS, emphasizing the importance of local treatment strategy for primary lesions during the whole course of the disease." (PMID 36153486, 2022).
lung adenocarcinoma (continued). "The reduced dose frequency resulted in therapeutic efficacy comparable to free drug in vivo in terms of 100% survival and reduced tumor burden along with downregulation of epidermal growth factor receptor, folate receptor α and peptide deformylase expression in lung adenocarcinoma mice model." (PMID 35892161, 2022). "DNA methylation in EGFR has been proposed as a predictive biomarker for lung adenocarcinoma." (PMID 35681244, 2022). "HPV 16E6/18E6 and EGFR expression serve as good prognostic factors in lung adenocarcinoma patients." (PMID 36358752, 2022). "Mutations in EGFR, ATM, and PIK3CA may provide new ideas for predicting TMB in lung adenocarcinoma patients." (PMID 35521981, 2022). "Systemic EGFR antagonists are now commonly used in lung adenocarcinoma therapy, and shorter-course therapy at the onset of exacerbation may be more tolerable." (PMID 35239513, 2022). "It has been suggested that the analysis of HSPH1 expression levels may help in predicting the effectiveness of chemotherapeutic approaches acting on the EGFR-TKI pathway in advanced lung adenocarcinoma." (PMID 36298586, 2022). "According to our results, we expect that both EGFR-targeted therapy and immunotherapy might change the histological composition of lung adenocarcinoma." (PMID 35016696, 2022). "Not all lung adenocarcinoma (LUAD) patients with activating epidermal growth factor receptor (EGFR) mutations respond to tyrosine kinase inhibitors (TKIs) as intended." (PMID 35590371, 2022). "Furthermore, a APCDD1L-AS1-miR-1322/miR-1972/miR-324-3p-SIRT5 axis has been investigated to facilitate icotinib-resistance by suppressing autophagic degradation of EGFR in lung adenocarcinoma." (PMID 35350778, 2022). "Additionally, it has been documented that a APCDD1L-AS1-miR-1322/miR-1972/miR-324-3p-SIRT5 axis facilitated icotinib-resistance by suppressing autophagic degradation of EGFR in lung adenocarcinoma." (PMID 35350778, 2022). "Cutaneous melanoma and lung adenocarcinoma contained the largest number of patients with an approved actionable marker detected by all sequencing types which was due to the high prevalence of BRAF V600 hotspot and EGFR mutations, respectively." (PMID 35849877, 2022). "Moreover, this mutant KRAS signature was significantly positively enriched in KRAS- versus EGFR (epidermal growth factor receptor)-mutant LUAD (lung adenocarcinoma; GSE43458) from the BATTLE trial." (PMID 35327394, 2022). "Another protein that interacts with hTid-1 through the DnaJ domain is the Receptor Tyrosine Kinase (RTK), and EGF Receptor (EGFR) which is a key driver protein of lung adenocarcinoma by regulating tumorigenic processes including invasion, angiogenesis, and apoptosis." (PMID 35854300, 2022). "All ERBB2 mutated patients were diagnosed with lung adenocarcinoma, were never smokers, and wild‐type for EGFR, KRAS, and ALK hotspot alterations." (PMID 36251951, 2022). "Here, EGFR/ALK-wild type lung adenocarcinoma was set as the reference for comparison." (PMID 35980949, 2022). "Of the non-small-cell lung cancer (NSCLC) patients, epidermal growth factor receptor (EGFR) mutations account for approximately 30% of cases in China, 12% in the USA, and 10% in France and are most common among patients with lung adenocarcinoma (LUAD)." (PMID 35590371, 2022). "Consequently, the purpose of the current study was to evaluate the effect of GAS5 SNP plus EGFR phenotypes on the clinical manifestations of lung adenocarcinoma." (PMID 36011604, 2022). "Such EGFR mutations of lung adenocarcinoma are more frequently observed in women, nonsmoker, and Asian populations." (PMID 35664735, 2022). "hTid-1 interacts with EGFR/HSP70/HSP90 via its DnaJ domain and induces poly-ubiquitination resulting in subsequent proteasomal degradation of EGFR, thereby downregulating its expression levels and hence acting as a deterrent in the progression of lung adenocarcinomas." (PMID 35854300, 2022).
lung adenocarcinoma (continued). "EGFR and KRAS are the most frequently mutated oncogenes in human lung adenocarcinoma." (PMID 35368709, 2022). "In conclusion, these data indicate that the GAS5 SNP rs145204276 variant may help predict tumor stage, lymph node metastasis and distal metastases in patients with EGFR wild type lung adenocarcinoma." (PMID 36011604, 2022). "The histone deacetylase inhibitor vorinostat could promote ferroptosis in EGFR-mutant lung adenocarcinoma cells by inhibiting SLC7A11 (xCT) expression and enhancing the efficacy of ferroptosis inducers." (PMID 35151318, 2022). "Similarly, our study has addressed the synergistic effect of HPV 16E6/18E6 and EGFR expression on the survival outcome in a lung adenocarcinoma cohort." (PMID 36358752, 2022). "It has been identified that most of the driver gene alterations in lung adenocarcinoma in never-smokers include EGFR, KRAS mutations, and so on." (PMID 35991047, 2022). "The present study examined the relationship between the GAS5 single-nucleotide polymorphisms (SNPs; rs145204276 Ins/Del, rs55829688 T/C) and the clinicopathological factors in 539 lung adenocarcinoma patients with or without EGFR mutations." (PMID 36011604, 2022). "PFS was significantly better for classical mutations than for non-classical mutations in patients with EGFR mutated lung adenocarcinoma combined with pleural effusion at initial diagnosis." (PMID 35340158, 2022). "This could be a hypothesis worth exploring, given the association between female sex and EGFR mutations, and the possible mechanistic pathway for TB-induced lung adenocarcinoma, which some hypothesize could involve the EGFR pathway." (PMID 35140255, 2022). "NNK, a β-adrenergic (β-ARs) agonist, is capable of stimulating DNA synthesis and proliferation of human pancreatic duct epithelial cells lung adenocarcinoma cells via the β-ARs release of arachidonic acid or trans-activation of epidermal growth factor receptor (EGFR) by initiating cAMP signaling." (PMID 35878269, 2022). "This is the first known report of a patient with advanced NSCLC, advanced non-smoking lung adenocarcinoma, and no EGFR mutation who survived for nearly 12 years by comprehensive treatment based on EGFR-TKI-based therapy." (PMID 35029237, 2022). "Molecular techniques are of major importance, for example, concerning the EGFR gene, which is mutated in 10–15% of non-Asian patients and in 40–60% of Asian patients with lung adenocarcinoma." (PMID 35885495, 2022). "For the patients with advanced EGFR-mutant lung adenocarcinoma, the radical thoracic radiotherapy dose scheme (≥ 60 Gy) could significantly prolong the OS of patients during the whole course management." (PMID 36153486, 2022). "In particular, OS was improved in patients with lung adenocarcinoma harboring the EGFR 19 del mutation but not in patients with EGFR L858R or in the EGFR mutation-positive patient population overall." (PMID 36508072, 2022). "This study showed that, for the patients with advanced EGFR-mutant lung adenocarcinoma, the radical thoracic radiotherapy dose scheme (≥ 60 Gy) could significantly prolong the OS of patients during the whole course management." (PMID 36153486, 2022). "Previous studies have found that some clinical variables such as female, non-smokers, patients with histological type of lung adenocarcinoma, and East Asian populations are significantly associated with EGFR mutations." (PMID 35574401, 2022). "In a Phase II trial of non-diabetic stage IIIB/IV patients with EGFR-mutated lung adenocarcinoma, the addition of metformin to EGFR tyrosine kinase resulted in improved PFS and OS." (PMID 36591457, 2022). "Several studies have identified smoking as a negative predictive marker for EGFR mutation status in patients with lung adenocarcinoma or NSCLC." (PMID 36341427, 2022). "The platelets of the high D-dimer plasma may become a therapeutic target to improve the efficacy of EGFR TKI in patients with mutant lung adenocarcinoma." (PMID 35756605, 2022).
lung adenocarcinoma (continued). "Despite this, the use of EBUS TBNA could help to increase survival in recurrent lung adenocarcinoma patients with wild-type EGFR." (PMID 36292235, 2022). "On the other hand, there may not be strong relationships between the distribution frequencies of GAS5 SNP rs55829688 and the clinicopathologic characteristics of lung adenocarcinoma in all EGFR genotypes (all p > 0.05)." (PMID 36011604, 2022). "This study aimed to analyze the clinicopathological factors related to the relapse-free survival (RFS) of patients with pathological stage IB-IIIA primary lung adenocarcinoma with and without an EGFR mutation." (PMID 36085020, 2022). "Our case is of significant importance to clinicians involved in the treatment of patients with advanced nonsmoking lung adenocarcinoma and no epidermal growth factor receptor mutations." (PMID 35029237, 2022). "This study represents the first large cohort study to evaluate the efficacy and tolerability of EGFR-TKIs in EGFR-mutated lung adenocarcinoma patients with PS ≥ 2, as such patients are typically not included in clinical trials." (PMID 35158940, 2022). "Thus, it was possible to detect IDH mutation status and PTEN mutation status in gliomas, KRAS status in patients with colorectal carcinoma, and EGFR status in lung adenocarcinoma." (PMID 35884409, 2022). "The H1975 cell line originated from a non-smoker female with lung adenocarcinoma and is considered highly invasive, with a mutation that confers resistance to EGFR inhibitors." (PMID 36358570, 2022). "In conclusion, the presence of the GAS5 SNP rs145204276 variant could lead to advanced clinicopathological characteristics of lung adenocarcinoma under the presence of the EGFR wild type." (PMID 36011604, 2022). "Therefore, we performed this retrospective, real-world analysis for EGFR-mutant lung adenocarcinomas with BM to confirm the optimal brain radiotherapy regimen." (PMID 34847914, 2021). "We have developed a preclinical orthotopic mouse model, using luciferase tagged lung adenocarcinoma cells harboring EGFR TKI sensitive exon 19 deletion to model and extend trial implications comparing a weekly vs daily dosing outcome of osimertinib to a first-generation TKI- erlotinib." (PMID 33993094, 2021). "Indeed, targeted small molecule drugs called EGFR tyrosine-kinase inhibitors (EGFR TKI) have been shown to be highly effective in the treatment of lung adenocarcinomas." (PMID 35052732, 2021). "We also found out that the frequency of EGFR gene mutations in lung adenocarcinoma was higher in the never-smoker (69.7%) compared with the patient with previous tobacco exposure (15.3%), which was concordant with other previous studies." (PMID 34181354, 2021). "In addition, USP8 expression was correlated with EGFR mutation status and patients who had USP8-positive lung adenocarcinoma had significantly poorer outcomes than those who were USP8-negative." (PMID 34081623, 2021). "In clinical, PHLPP expression were reduced in the post-relapse tumor compared to that of pre-treatment, and lower pre-treatment PHLPP levels were significantly correlated with shorter progression-free survival (PFS) in patients with EGFR-mutant lung adenocarcinoma whom treated with EGFR-TKI." (PMID 34168988, 2021). "One of the most significant molecular differences in never-smoker and smoker lung adenocarcinoma is EGFR gene mutations." (PMID 34181354, 2021). "It was of interest to clarify whether c-Src overactivation was able to affect EGFR activation in lung adenocarcinoma." (PMID 34367939, 2021). "The reciprocal crosstalk between EGFR and MET in lung adenocarcinoma suggests that simultaneous inhibition through the combined use of EGFR-TKI and MET-TKI would benefit and potentially improve the survival outcomes of patients with concurrent EGFR and MET aberrations." (PMID 34660287, 2021). "Besides this, GLI1 also supports the EMT process leading to resistance to EGFR-TKIs in EGFRm lung adenocarcinoma." (PMID 34771484, 2021).
lung adenocarcinoma (continued). "Notably, aberrant mutations of EGFR, BRAF, or KRAS occurred in lung adenocarcinomas in a mutually exclusive manner." (PMID 34884633, 2021). "We also studied whether targeting YAP‐p62 signaling and YAP inhibitor verteporfin can be used to suppress EGFR‐TKI resistance in lung adenocarcinoma." (PMID 33486901, 2021). "EGFR mutations have been identified in up to 20% of all lung adenocarcinomas and there is a higher prevalence among females and non-smokers." (PMID 34439273, 2021). "p-Src and p-Casp8 were ubiquitous in EGFR-mutant lung adenocarcinomas." (PMID 34367939, 2021). "ICI therapy has been ineffective as second line therapy in EGFR mutant lung adenocarcinoma." (PMID 34638461, 2021). "NF1‐mutant lung adenocarcinoma patients had inferior disease‐free survival (DFS), and overall survival (OS) compared to those with the EGFR-mutation, and downregulation of NF1 expression caused by truncating mutations was reported to confer resistance to EGFR-TKI in lung adenocarcinoma patients." (PMID 34195081, 2021). "EGFR mutation-positive lung adenocarcinoma is well-known as a non-smoker type, whereas EGFR mutation-negative lung adenocarcinoma is a smoker type, and smoking has been reported to induce a high tumor mutation burden." (PMID 34445227, 2021). "Patients with EGFR mutations were more likely to be female, of Asian ethnicity, never-smokers, and be diagnosed with lung adenocarcinoma." (PMID 34055528, 2021). "It has been shown that YAP is upregulated in EGFR-TKI-resistant lung adenocarcinoma, which may be mediated by an Akt and MAPK-independent PI3K/PDK1 pathway." (PMID 33562150, 2021). "In our recently published data, among 814 patients with lung adenocarcinoma, EGFR gene alteration was observed in 503 (61.8%) patients, and the EGFR gene alteration was frequently found in papillary adenocarcinoma (79.8%), acinar adenocarcinoma (72.4%), and lepidic adenocarcinoma (55.3%)." (PMID 34234879, 2021). "However, a study assessing CNVs in ErbB genes found that half of all lung adenocarcinomas have CNVs of EGFR, ERBB2, ERBB3 and ERBB4, with higher CNV number corresponding to poorer prognosis." (PMID 34274969, 2021). "Finally, analysis of The Cancer Genome Atlas Program (TCGA) data reveals that the TKI-increased and GC-blocked ligands signature can predict an adverse prognosis in EGFR active mutant lung adenocarcinoma patients, who would be treated with EGFR TKIs." (PMID 34853306, 2021). "We report that DT induces regression of murine lung adenocarcinomas that express human mutant EGFR in the absence of a transgenic DTR allele." (PMID 34494649, 2021). "Our findings suggest that not only loss of neoantigens, but also reduced global landscape of antigen presentation may induce immune escape in EGFR mutant lung adenocarcinoma." (PMID 34638461, 2021). "Therefore, we expected to uncover a novel path to sensitize TKIs in EGFR-mutant lung adenocarcinomas." (PMID 34367939, 2021). "Because mutations in oncogenes such as EGFR and KRAS have been shown to occur in lung adenocarcinoma, the presence of KRAS and EGFR mutations in CMPTs has been hypothesized to be associated with lung adenocarcinoma by some investigators." (PMID 33960670, 2021). "EGFR, which encodes a receptor tyrosine kinase, is more frequently amplified in glioblastomas, whereas LRP1B, which encodes a low-density lipoprotein receptor related protein, is predominantly deleted in lung adenocarcinomas (LUAD)." (PMID 34395272, 2021). "The uniform lack of actionable gene alterations of conventional lung adenocarcinomas; namely, EGFR mutation, EML4-ALK rearrangement, and ROS1 rearrangement are common knowledge with regards to the SMARCA4-dNSCLC tumors." (PMID 34440689, 2021). "Additional epidermal growth factor receptor (EGFR) mutations confer the drug resistance to generations of EGFR targeted tyrosine kinase inhibitor (EGFR-TKI), posing a major challenge to developing effective treatment of lung adenocarcinoma (LUAD)." (PMID 34217295, 2021).